SERPINA6 (serpin family A member 6)
Description:
Major transport protein for glucocorticoids and progestins in the blood of almost all vertebrate species.
Synonyms: CBG
Tractability: Small molecule: a structure with a bound ligand is known. Antibody: its Gene Ontology location is reachable by antibodies, with high confidence; UniProt places it where antibodies can reach, with medium confidence; UniProt predicts a signal peptide or a membrane-spanning region. PROTAC: a small molecule that binds it is known.
Target class: Secreted protein
Gene: Protein-coding gene on chromosome 14 (94,304,248 to 94,323,389, reverse strand). Ensembl gene ENSG00000170099.
Subcellular location: Secreted
Pathways (Reactome):
Drug ADME: Prednisone ADME
Metabolism: Glucocorticoid biosynthesis
Gene Ontology:
Molecular function: molecular carrier activity; steroid binding; serine-type endopeptidase inhibitor activity
Biological process: glucocorticoid biosynthetic process
Cellular component: extracellular exosome; extracellular region
Genetic constraint (gnomAD): Loss-of-function variants: 20 observed, 28.83 expected, observed/expected ratio (o/e) 0.69, 90% interval 0.49 to 1.01. The upper end of that interval is the gene's LOEUF score, 1.01, which puts it in group 4 of 6, group 1 being the genes least tolerant of losing a copy. Missense variants: 473 observed, 530.96 expected, observed/expected ratio (o/e) 0.89, 90% interval 0.82 to 0.96. Synonymous variants: 196 observed, 211.34 expected, observed/expected ratio (o/e) 0.93, 90% interval 0.82 to 1.04.
Homologues: Orthologues: chimpanzee SERPINA6 (98% identical), macaque SERPINA6 (94% identical), dog SERPINA6 (70% identical), rabbit SERPINA6 (69% identical), pig SERPINA6 (66% identical), rat Serpina6 (61% identical), mouse Serpina6 (58% identical), guinea pig SERPINA6 (53% identical). Paralogues in human: SERPINA3 (45% identical), SERPINA4 (43% identical), SERPINA9 (42% identical), SERPINA1 (42% identical), SERPINA5 (41% identical), SERPINA7 (40% identical), SERPINA11 (38% identical), SERPINA12 (31% identical), SERPINB6 (31% identical), SERPIND1 (30% identical), SERPINB9 (30% identical), SERPINB1 (29% identical), and 24 more.
Diseases named in the same sentence as SERPINA6 in open-access papers:
SERPINA6 is named in the same sentence as 50 diseases in open-access papers, as found by Europe PMC text mining. Sharing a sentence is not in itself a finding about the gene and the disease. The quoted sentences say what the papers report.
Obesity (6 papers, 2014 to 2025). Accumulation of substantial excess body fat. "SERPINA6 has been associated with obesity and stress sensitivity, and excessive obesity in pigs affects the pork’s yield and quality." (PMID 39199880, 2024). "Common BAD and SERPINA6 variants were associated (p<0.05) with obesity and insulin resistance, respectively." (PMID 29126409, 2017). "The availability of CBG-deficient mice produced by specific knockout of the SerpinA6 gene provided the opportunity to clarify the specific role of CBG in obesity." (PMID 28066325, 2016). "CA3 is associated with the internal fat rate and backfat thickness ofthe pig, while SERPINA6 within the quantitative trait loci is associated with cortisol levels, fat, and muscle content, so can be considered a key regulator of obesity susceptibility." (PMID 25053997, 2014). "As previously seen, some polymorphisms in the SERPINA6 gene have been associated with decreased plasma CBG concentrations and certain obesity-related parameters, such as insulin resistance." (PMID 41180195, 2025).
metabolic syndrome (5 papers, 2005 to 2021). A cluster of metabolic risk factors for CARDIOVASCULAR DISEASES and TYPE 2 DIABETES MELLITUS. "Although, none of the SNPs tested were associated with odds of presenting with the metabolic syndrome, rs17090691-G in the SERPINA6/A1 region, showed an association with higher diastolic blood pressure in the sample comprising both sexes." (PMID 34484290, 2021). "Hence, the primary aim of this study was to investigate the associations between CYP171A and SERPINA6/A1 SNPs and the metabolic syndrome and its related cardiometabolic risk factors, in black South African men and women." (PMID 34484290, 2021). "However, associations between SNPs at SERPINA6/A1 and the metabolic syndrome and related cardiometabolic risk factors remain to be investigated." (PMID 34484290, 2021). "Based on these previous findings, the present study investigated whether common genetic variants at both CYP17A1 and SERPINA6/A1 loci are associated with the metabolic syndrome, its related cardiometabolic risk factors, and circulating glucocorticoids, in black South Africans." (PMID 34484290, 2021). "Furthermore, rare mutations in SERPINA6 may be associated with hypertension, fatigue and metabolic syndrome." (PMID 24691024, 2014).
breast carcinoma (3 papers, 2020 to 2024). "SERPINA6 is related to chemotherapy resistance in breast cancer." (PMID 34706720, 2021).
Cirrhosis (3 papers, 2012 to 2025). A chronic disorder of the liver in which liver tissue becomes scarred and is partially replaced by regenerative nodules and fibrotic tissue resulting in loss of liver function. "In situations where CBG is reduced (sepsis, cirrhosis, nephrotic syndrome, hyperthyroidism and SERPINA6 gene polymorphisms), low cortisol values must be interpreted with caution." (PMID 34512551, 2021). "Corticosteroid-binding globulin (gene SERPINA6) is decreased in cirrhosis compared to healthy controls and our Western blot data showed that this marker was high in healthy controls and generally lower in Ishak stages 1–6." (PMID 22761838, 2012).
Hypertension (3 papers, 2014 to 2025). The presence of chronic increased pressure in the systemic arterial system. "A genetic variant of Serpina6 causing reduced cortisol-binding affinity has been associated with hypertension." (PMID 37660920, 2023).
COVID-19 (2 papers, 2021 to 2022). A disease caused by infection with severe acute respiratory syndrome coronavirus 2. "Further, the deep plasma proteome study of non-severe versus severe COVID-19 patients revealed only 38 differentially expressed proteins, out of which proteins such as FGG, S100A8, VWF, SAA4, SERPIND1, and SERPINA6 were identified to be significantly upregulated in the COVID-19 severe patients." (PMID 33995121, 2021).
Hyperglycemia (2 papers, 2017 to 2020). An increased concentration of glucose in the blood. "However, because data was not available, we could not determine if SERPINA6 variants were associated with the development of hyperglycemia during ALL treatment." (PMID 29126409, 2017).
Insulin resistance (2 papers, 2017 to 2023). Increased resistance towards insulin, that is, diminished effectiveness of insulin in reducing blood glucose levels. "An additive effect was observed for the common variant rs2228541 (SERPINA6) and insulin resistance (p=0.05)." (PMID 29126409, 2017). "Moreover, insulin resistance was associated with a common variant in Serpin Family A Member 6 (SERPINA6) (FDR 0.07)." (PMID 29126409, 2017). "The variant rs2228541 in SERPINA6 was associated with a decreased risk of insulin resistance." (PMID 29126409, 2017). "Along the same lines, increased levels of SERPINA6 have been identified in obese patients and are reported to play a crucial role in glucose homeostasis, along with reducing insulin resistance and inflammation." (PMID 37686344, 2023).
liver disease (2 papers, 2014 to 2023). "Current researches have suggested a potential role of SERPINA6 in liver diseases." (PMID 25198130, 2014).
benign prostate hyperplasia (1 paper, 2022). "Corticosteroid-binding globulin (Serpina6) was detected in prostate tissue from patients with benign prostate hyperplasia." (PMID 35886909, 2022).
bladder cancer (1 paper, 2025). "In cisplatin-resistant bladder cancer cell lines, FLRT2, HOXC5, SCD, GRM7, HMGA1, ETV7, and SCO2 were highly expressed, while EMP1, SERPINA6, and ZNF124 exhibited lower expression levels." (PMID 39744172, 2025).
Cachexia (1 paper, 2020). Severe weight loss, wasting of muscle, loss of appetite, and general debility related to a chronic disease. "Four were common for local/cachexia (C1R, PRKCG, ELANE, SOST: all oppositely regulated) and four for metastatic/cachexia (SERPINA6, PDGFRA, PRSS2, PRSS1: all consistently changed), suggesting that stage and cachexia status might be molecularly separable." (PMID 33334063, 2020).
congenital cataracts (1 paper, 2022). "Group 5 (congenital cataracts) also shows abundant proteins involved in protein metabolism, among which three proteins—corticosteroid-binding globulin-SERPINA6, apolipoprotein A-IV (APOA4), and inter-alpha-trypsin inhibitor heavy chain H4 (ITIH4)—were downregulated compared to other groups." (PMID 36362243, 2022).
diabetes (1 paper, 2021). "Within their gene families SERPINA6, SERPINB2, and SERPINB8 have long been known as biomarkers for diabetes." (PMID 34178943, 2021).
emphysema (1 paper, 2019). "In more detail, HLA-DPB1 is a known COPD gene related to disease severity, SERPINA6 was associated with emphysema, a deletion in ADORA2B was shown to be associated with a decrease in lung fibrosis and pulmonary hypertension, and ELMOD2 is a candidate gene for familial idiopathic pulmonary fibrosis." (PMID 30845926, 2019).
hemolysis (1 paper, 2025). Disruption of the integrity of the erythrocyte membrane causing release of hemoglobin. "Among the top 30 proteins with highest variance were 12 immunoglobulins (CV between 22.0% and 89.2%), 4 hemolysis-related proteins (CV between 26.9% and 54.5%) as well as the hormone transporters transcortin (SERPINA6, CV = 48.3%) and sex hormone binding globulin (SHBG, CV = 123.3%)." (PMID 40263456, 2025).
liver cirrhosis (1 paper, 2014). "Decreased circulating SERPINA6 concentrations were observed in patients with liver cirrhosis." (PMID 25198130, 2014).
melanoma (1 paper, 2012). A malignant, usually aggressive tumor composed of atypical, neoplastic melanocytes. "Among the top markers, OAS3 and SERPINA6 are predicted to be blood secretory by our prediction program, hence suggesting the potential feasibility in identifying diagnostic markers for melanoma through blood tests." (PMID 22295108, 2012).
postpartum depression (1 paper, 2022). A type of clinical depression that occurs after childbirth. "SERPINA6 was involved in HPA axis regulation and was associated with antenatal and postpartum depression." (PMID 36699448, 2022).
prostate carcinoma (1 paper, 2022). A carcinoma that arises from epithelial cells of the prostate gland. "The clustering yielded a clear pattern of the five upregulated EV proteins (i.e., SERPINA3, SCGB3A1, LRG1, SERPINA6, and CP) enriched in the prostate cancer cases." (PMID 36500247, 2022).
type 2 diabetes (1 paper, 2014). "Some studies have indicated an association between SERPINA6 and type 2 diabetes too." (PMID 25198130, 2014).
tumor (6 papers, 2012 to 2025). "Targeting SERPINA6, which acts as a glucocorticoid receptor agonist, may inhibit tumor progression by regulating stress responses and inflammatory processes." (PMID 40170854, 2025). "These include hormone transport, as observed with cortisol binding globulin (CBG) (SERPINA6) and thyroxine binding globulin (TBG) (SERPINA7), molecular chaperoning (SERPINH7) or tumour suppression (SERPINB5)." (PMID 34198546, 2021).
metabolic disease (3 papers, 2013 to 2025). A congenital disorder (due to inherited enzyme abnormality) or acquired (due to failure of a metabolically important organ) disorder resulting from an abnormal metabolic process. "Impaired expression of SERPINA6 is correlated with cardiovascular and metabolic diseases." (PMID 40243422, 2025).
SERPINA6 also shares sentences with these, for which no sentence is quoted: cancer (3 papers); cardiovascular disease (3); Sepsis (3); Cushing syndrome (2); Hypoalbuminemia (2); acute pancreatitis (1); Adrenal insufficiency (1); bladder tumor (1); chronic hepatitis C (1); Cognitive impairment (1); coronary artery calcification (1); cystic fibrosis (1); endocrine disorders (1); familial idiopathic pulmonary fibrosis (1); Huntington disease (1); hyperthyroidism (1); lung fibrosis (1); nephrotic syndrome (1); neurodegenerative disease (1); orofacial cleft (1); ovarian carcinoma (1); Parkinson disease (1); peripheral nerve injury (1); prostate hyperplasia (1); pulmonary hypertension (1); rheumatoid arthritis (1); Stroke (1).